NOD1 (nucleotide binding oligomerization domain containing 1)
Description:
Pattern recognition receptor (PRR) that detects bacterial peptidoglycan fragments and other danger signals and thus participates in both innate and adaptive immune responses. Specifically recognizes and binds gamma-D-glutamyl-meso-diaminopimelic acid (iE-DAP), a dipeptide present in peptidoglycan of Gram-negative bacteria. Preferentially binds iE-DAP in tripeptide-containing muropeptides (MurNAc-TriDAP or TriDAP). Ligand binding triggers oligomerization that facilitates the binding and subsequent activation of the proximal adapter receptor-interacting RIPK2. Following recruitment, RIPK2 undergoes 'Met-1'- (linear) and 'Lys-63'-linked polyubiquitination by E3 ubiquitin-protein ligases XIAP, BIRC2, BIRC3 and the LUBAC complex, becoming a scaffolding protein for downstream effectors, triggering activation of the NF-kappa-B and MAP kinases signaling. This in turn leads to the transcriptional activation of hundreds of genes involved in immune response. Also acts as a regulator of antiviral response elicited by dsRNA and the expression of RLR pathway members by targeting IFIH1 and TRAF3 to modulate the formation of IFIH1-MAVS and TRAF3-MAVS complexes leading to increased transcription of type I IFNs. Also acts as a regulator of autophagy via its interaction with ATG16L1, possibly by recruiting ATG16L1 at the site of bacterial entry (By similarity). Besides recognizing pathogens, also involved in the endoplasmic reticulum stress response: acts by sensing and binding to the cytosolic metabolite sphingosine-1-phosphate generated in response to endoplasmic reticulum stress, initiating an inflammation process that leads to activation of the NF-kappa-B and MAP kinases signaling. In addition, plays a role in insulin trafficking in beta cells in a cell-autonomous manner (By similarity). Mechanistically, upon recognizing cognate ligands, NOD1 and RIPK2 localize to insulin vesicles where they recruit RAB1A to direct insulin trafficking through the cytoplasm (By similarity). [Isoform 3]: In contrast to isoform 1, does not efficiently recognize and bind gamma-D-glutamyl-meso-diaminopimelic acid (iE-DAP) ligand.
Synonyms: hNod1; CARD4; NLRC1; CLR7.1
Tractability: Small molecule: a high-quality ligand is known; it has a binding pocket of medium quality; it belongs to a druggable protein family. Antibody: UniProt places it where antibodies can reach, with high confidence; its Gene Ontology location is reachable by antibodies, with high confidence. PROTAC: UniProt records ubiquitination sites on it; ubiquitination databases record sites on it; a small molecule that binds it is known.
Chemical probes: ML130, ML146
Gene: Protein-coding gene on chromosome 7 (30,424,527 to 30,478,789, reverse strand). Ensembl gene ENSG00000106100.
Subcellular location: Cell membrane; Apical cell membrane; Basolateral cell membrane; Cytoplasm
Subcellular location (Human Protein Atlas): Mitochondria
Pathways (Reactome):
Immune System: Interleukin-1 signaling; JNK (c-Jun kinases) phosphorylation and activation mediated by activated human TAK1; NOD1/2 Signaling Pathway; TAK1-dependent IKK and NF-kappa-B activation; activated TAK1 mediates p38 MAPK activation
Disease: SARS-CoV-2 activates/modulates innate and adaptive immune responses
Metabolism of proteins: Ovarian tumor domain proteases
Gene Ontology:
Molecular function: CARD domain binding; identical protein binding; pattern recognition receptor activity; peptidoglycan binding; protein binding; protein homodimerization activity; protein-containing complex binding; ubiquitin binding; cysteine-type endopeptidase activator activity involved in apoptotic process
Biological process: cellular response to muramyl dipeptide; defense response to bacterium; defense response to Gram-negative bacterium; detection of bacterium; intracellular signal transduction; nucleotide-binding oligomerization domain containing 1 signaling pathway; pattern recognition receptor signaling pathway; positive regulation of canonical NF-kappaB signal transduction; positive regulation of interleukin-8 production; positive regulation of non-canonical NF-kappaB signal transduction; apoptotic process; defense response; detection of biotic stimulus; inflammatory response; positive regulation of dendritic cell antigen processing and presentation; signal transduction; positive regulation of apoptotic process; positive regulation of autophagy; positive regulation of cytokine production; positive regulation of interleukin-1 beta production; positive regulation of tumor necrosis factor production; regulation of apoptotic process; response to endoplasmic reticulum stress
Cellular component: apical plasma membrane; basolateral plasma membrane; cytoplasm; cytosol; plasma membrane; phagocytic vesicle
Genetic constraint (gnomAD): Loss-of-function variants: 55 observed, 70.22 expected, observed/expected ratio (o/e) 0.78, 90% interval 0.63 to 0.98. The upper end of that interval is the gene's LOEUF score, 0.98, which puts it in group 4 of 6, group 1 being the genes least tolerant of losing a copy. Missense variants: 1,175 observed, 1,218.5 expected, observed/expected ratio (o/e) 0.96, 90% interval 0.92 to 1.01. Synonymous variants: 484 observed, 530.1 expected, observed/expected ratio (o/e) 0.91, 90% interval 0.85 to 0.98.
Homologues: Orthologues: chimpanzee NOD1 (99% identical), macaque NOD1 (96% identical), dog NOD1 (84% identical), rabbit NOD1 (82% identical), mouse Nod1 (82% identical), rat Nod1 (82% identical), guinea pig NOD1 (74% identical), tropical clawed frog nod1 (52% identical), zebrafish nod1 (46% identical). Paralogues in human: NOD2 (33% identical), NLRP12 (20% identical), NLRP3 (20% identical), NLRC3 (19% identical), NLRC5 (19% identical), CIITA (19% identical), NLRP4 (18% identical), NLRP2 (18% identical), NLRP14 (18% identical), NLRP7 (18% identical), NLRP1 (18% identical), NLRP9 (18% identical), and 8 more.
Diseases named in the same sentence as NOD1 in open-access papers:
NOD1 is named in the same sentence as 218 diseases in open-access papers, as found by Europe PMC text mining. Sharing a sentence is not in itself a finding about the gene and the disease. The quoted sentences say what the papers report.
Insulin resistance (32 papers, 2012 to 2025). Increased resistance towards insulin, that is, diminished effectiveness of insulin in reducing blood glucose levels. "Both adipocyte cell models and in vivo studies on human adipose tissue have served to establish the association of insulin resistance to both NOD1 and NOD2 activities by eliciting pro-inflammatory signaling pathways." (PMID 39200288, 2024). "It has been found that people with the NOD1 (Glu266Lys) Lys/Lys genotype are affected by saturated fatty acids, increasing the risk of insulin resistance." (PMID 39906040, 2024). "In animal models, NOD1 has been shown to contribute to the development of insulin resistance and metabolic syndromes caused by the high-fat diet (HFD)." (PMID 36268029, 2022). "We previously showed that Nucleotide-binding oligomerization domain-containing protein 1 (NOD1) activation with bacterial peptidoglycan (PGN) caused insulin resistance in mice." (PMID 24828250, 2014). "This upregulation of NOD1, particularly in skeletal muscle, adipose tissue, and the liver, has been associated with an intensified inflammatory response and was causally linked to both peripheral and hepatic insulin resistance." (PMID 41226484, 2025). "Moreover, administration of gefitinib, a RIPK2 inhibitor, attenuated metabolic inflammation and insulin resistance caused by NOD1 activation." (PMID 36268029, 2022). "Moreover, insulin resistance has been associated with both NOD1 and NOD2 activities by eliciting pro-inflammatory signaling pathways in adipocyte cell models and in in vivo studies on human adipose tissue." (PMID 32704052, 2020). "Likewise, high-fat diet (HFD)-induced translocation of intestinal bacteria into adipose tissue and blood as well as insulin resistance is prevented in NOD1-deficient mice." (PMID 32588196, 2020). "In addition, PGN can cause acute systemic insulin resistance by activating NOD1, and NOD1-deficient mice have reduced bacterial translocation to metabolic tissues and improved insulin tolerance." (PMID 31582899, 2019). "NOD1-activating bacterial PGN motifs can also cause acute systemic insulin resistance in mice." (PMID 23482058, 2013). "In general, postbiotics that activate NOD1 activate a proinflammatory nuclear factor kappa-light-chain-enhancer of activated B cells (NF-κB) cascade, which promotes metabolic inflammation and insulin resistance." (PMID 39235984, 2025). "The totality of the tissue-specific effects of NOD1 activation leads to whole-body insulin resistance, dysglycemia, and metabolic inflammation, all of which require RIPK2." (PMID 39235984, 2025). "Specifically, it has been shown that the activation of NOD1 reduces insulin-induced glucose uptake, indicating a direct link between innate immunity and insulin resistance in human adipocytes." (PMID 41226484, 2025). "The Nuclear factor of activated T cells (NFAT) is highly expressed in monocytes of individuals diagnosed with type 2 diabetes and is positively correlated with NOD1, insulin resistance, and blood glucose levels." (PMID 39906040, 2024). "Synergizing with intestinal TLR4, the nucleotide–oligomerization domain receptor (NOD)-1 has also been revealed as a key partner in developing insulin resistance." (PMID 39200288, 2024). "NOD1 triggers abnormal cellular metabolism, including glycolipid metabolism, and is involved in the development and progression of insulin resistance and cardiometabolic disease." (PMID 39906040, 2024). "Whole body or hematopoietic depletion of NOD1 significantly decreased high-fat diet (HFD)-associated glucose and insulin resistance in mice." (PMID 36920176, 2023). "Direct NOD1 activation led to insulin resistance while, conversely, NOD2 signaling is protective against Type 2 diabetes." (PMID 37373556, 2023).
Insulin resistance (continued). "Similar to the TLR system, the nucleotide-binding oligomerization domain contains the proteins NOD1 and NOD2, which are cytosolic receptors that respond to bacterial peptidoglycans and have been associated with the development of insulin resistance." (PMID 37373556, 2023). "Further support for the role of NOD1 in response to the HFD diet was obtained by injecting mice with the NOD1 ligand tetra-DAP, which was sufficient to cause whole-body insulin resistance and reduced glucose clearance." (PMID 37869013, 2023). "Metabolic inflammation and insulin resistance are driven by the sensing of translocated intestinal microbiota by NOD1, which is downregulated by the activation of NOD2." (PMID 36268029, 2022). "NOD1 activation participates in multiple biological processes, such as innate immune regulation, chronic inflammation, and insulin resistance." (PMID 35966130, 2022). "Expression of NOD1 in hematopoietic cells has been highlighted as a molecular mechanism accounting for the development of metabolic inflammation and insulin resistance." (PMID 36268029, 2022). "Understanding of neutrophil functions in NOD1-dependent whole-body insulin resistance and metabolic inflammations await further investigations." (PMID 35531300, 2022). "In parallel with the NOD1-mediated adipocyte and hepatocyte inflammations in insulin resistance, NOD2 activation by the corresponding PGN ligands in skeletal muscle cells also provoked insulin resistance via cell-autonomous innate immune responses." (PMID 35531300, 2022). "NOD1-mediated insulin resistance and obesity are negatively regulated by IRF4, which is induced by the activation of NOD2 with MDP." (PMID 36268029, 2022). "For example, a study of 25 Indian diabetic patients showed that diabetic monocytes had significant upregulation of both Nod1 (20 fold) and Nod2 (25 fold) transcripts that positively correlated with insulin resistance." (PMID 33503814, 2021). "In one study, the carriage of non-synonymous polymorphisms of NOD1 (rs2075820 [p.E266K]) and NOD2 (rs2066842 [p.S268P]) was examined for links with metabolic syndrome and insulin resistance in 998 Canadians aged 20–29." (PMID 33503814, 2021). "In stark contrast to the protective role of NOD1 loss in metabolic syndrome models, Nod2−/− mice fed a HFD had aggravated inflammation and obesity, as well as increased insulin resistance." (PMID 33503814, 2021). "Previous studies have shown promotion of adipose tissue inflammation, cellular insulin resistance, and impaired adipocyte differentiation upon NOD1 activation." (PMID 34165676, 2021). "A handful of studies have evaluated specific NOD1 and NOD2 polymorphisms to determine if they are associated with metabolic syndrome and insulin resistance." (PMID 33503814, 2021). "Both NOD1 and NOD2 have been linked with innate immune system activation in metabolic disease, including insulin resistance, diabetes, and liver steatosis." (PMID 33503814, 2021). "Accordingly, related to the previous comments on NOD1 activation in conditions of high glucose and diabetes, and its relationship with insulin resistance, this PRR expression is enhanced in the adipose tissue of women with gestational diabetes." (PMID 34066406, 2021). "Surprisingly, this protection appears to be mediated by actions of NOD1 in both hematopoietic and non-hematopoietic cell compartments, as a hematopoietic-specific Nod1 knockout mouse was only partially protected from HFD-induced insulin resistance." (PMID 33503814, 2021). "Direct NOD1 activation led to insulin resistance and gut microbial derived NOD1 ligands promoted insulin trafficking in beta cells." (PMID 33178196, 2020). "NOD1 and NOD2 are cytosolic receptors that respond to bacterial peptidoglycans and have been associated with the development of insulin resistance." (PMID 33178196, 2020).
Insulin resistance (continued). "In this context, double knockout NOD1/NOD2 mice are protected against peripheral insulin resistance and peripheral inflammation observed in the obesity (HFD)-induced T2D model." (PMID 32903730, 2020). "It is important to understand if bacterial PGN causes lipolysis through NOD1 or NOD2 because elevated circulating lipids and ectopic lipid deposition can promote insulin resistance in the liver and muscle." (PMID 24828250, 2014). "Accumulating evidence indicates that activation of NOD1 and NOD2 is associated with insulin resistance." (PMID 24064574, 2013). "Mechanistically, NOD1 disrupts insulin signaling and mediates insulin resistance." (PMID 39906040, 2024). "Thus, NOD1 not only functions as a PRR for intestinal bacterial components but also stimulates the development of insulin resistance and metabolic syndrome, including steatosis." (PMID 36268029, 2022). "Complementing these results are the findings that injection of the synthetic tetra-DAP NOD1 agonist FK156 into mice is sufficient to drive the onset of whole body insulin resistance and exacerbate glucose intolerance in HFD fed mice in a manner that required RIP2 expression." (PMID 33503814, 2021). "We showed that PGN containing meso-DAP motifs (generally dominant in Gram-negative bacteria) caused profound insulin resistance through actions on NOD1 directly in metabolic cells, including adipocytes and hepatocytes." (PMID 25666722, 2015). "We have shown that NOD1/2-double knockout mice are protected from high fat diet-induced obesity and insulin intolerance and that meso-DAP containing PGN causes inflammation and profound whole body insulin resistance via NOD1." (PMID 24828250, 2014). "Recent studies have associated NOD1- and NOD2-activating bacterial motifs with insulin resistance." (PMID 23482058, 2013). "Moreover, activation of NOD1 in hematopoietic cells can further promote changes in macrophage polarisation, shifting them towards a proinflammatory state, thereby amplifying systemic inflammation and insulin resistance." (PMID 41226484, 2025). "A clinical trial found that NOD1 and NOD2 mRNA expression in peripheral blood mononuclear cells from people with type 2 diabetes was positively correlated with insulin resistance and glycemic abnormalities." (PMID 39906040, 2024). "In addition, NOD1 expression in immune cells may contribute to insulin resistance." (PMID 39906040, 2024). "Accumulating evidence suggests that NOD1 activation triggers the NF-κB and MAPK pathways, facilitating insulin resistance in the liver and adipocytes." (PMID 38336763, 2024). "A role for NOD1 and NOD2 in HFD-induced insulin resistance was first demonstrated in Nod1/2−/− mice on a C57BL/6 background." (PMID 33503814, 2021). "Regarding insulin resistance and NLR activity, other groups have described that NOD1 activation after iE-DAP administration promotes insulin resistance." (PMID 32704052, 2020). "A fine balance between the activation of innate NOD1 and NOD2 receptors is crucial for maintaining peripheral insulin resistance." (PMID 32903730, 2020). "Intriguingly, the activation of either NOD1 or NOD2 leads to different outcomes in mouse models of T2DM: NOD1/2 double-knockout mice and NOD1 knockout mice were protected from HFD-induced insulin resistance." (PMID 31632962, 2019). "We propose that NOD1-activating PGN contributes to lipolysis and insulin resistance during metabolic endotoxemia." (PMID 24828250, 2014). "Peptidoglycan-induced activation of NOD1 in adipocytes or hepatocytes and NOD2 in muscle cells trigger insulin resistance through the production of inflammatory mediators and the activation of MAP kinases signaling leading to desensitization of IRS1 function." (PMID 23316186, 2012). "However, as we explored in section 5.1, NOD1 regulation of the IRS1/Akt pathway hinders insulin signaling, inducing insulin resistance." (PMID 39906040, 2024).